INS (insulin)
Diseases named in the same sentence as INS in open-access papers (continued):
Sharing a sentence is not in itself a finding about the gene and the disease.
Obesity (continued). "Carbohydrate-insulin model: does the conventional view of obesity reverse cause and effect?" (PMID 38884643, 2024). "We hypothesized that higher serum myostatin levels are associated with lower insulin sensitivity in otherwise healthy adults with overweight/obesity." (PMID 39261976, 2024). "Moreover, probiotics have been associated with reducing fat absorption, enhancing insulin sensitivity and boosting energy expenditure, all of which confer benefits in weight control and obesity prevention." (PMID 38892352, 2024). "Obesity is often associated with abnormal gene expression related to carbohydrate, lipid, and protein metabolism, particularly those involved in pathways linked to insulin resistance, as well as fatty acid and amino acid synthesis." (PMID 39458511, 2024). "Likewise, AdipoR agonist enhances insulin sensitivity and exercise endurance, extends the shortened lifespan associated with obesity, and recovers nonalcoholic steatohepatitis (NASH) and related fibrosis." (PMID 39872218, 2024). "In addition, elevated PAI-1 levels have been linked to the impairment of insulin signaling in obesity and in the establishment of a chronic inflammatory state, similar to the role played by IL-6, also upregulated in our model." (PMID 38396763, 2024). "Furthermore, the mRNA expression of Hox-c9 in the adipose tissue has been inversely related to obesity-related traits and positively associated with insulin sensitivity." (PMID 38613013, 2024). "Notwithstanding, a carbohydrate–insulin model has been proposed to integrate multiple causal factors affecting (i) circulating fuels, (ii) hepatic fat accumulation, and (iii) intestinal function, leading the establishment of the diet-induced obesity." (PMID 39200288, 2024). "This includes the effects of fat mass on cytokine production, insulin resistance, and lipid metabolism, all of which are crucial for understanding the physiological basis for depression and suicidal ideation linked to obesity." (PMID 38743203, 2024). "We hypothesize that HFD-induced obesity is associated with impaired whole-body and tissue level insulin sensitivity and worse blood glucose profile." (PMID 38651416, 2024). "Several factors, such as excessive nutrient intake, elevated dietary inflammatory index (DII), sedentary lifestyle, obesity, and psychological stress, can activate multiple pathways causing metabolic deregulation and decreased insulin sensitivity in insulin-respondent tissues." (PMID 38667278, 2024). "The bacterium normalized insulin levels even in a background of Rag1-deficiency, but this effect was not sufficient to alleviate glucose intolerance, suggesting a defect in insulin signaling caused by systemic inflammation in obesity." (PMID 38845049, 2024). "Low-CHO diets and a KD have emerged as alternative approaches for obesity management, demonstrating rapid weight loss and improvements in insulin sensitivity, but their suitability and long-term effects may vary based on gender-specific metabolic differences." (PMID 38892561, 2024). "IL-1β stimulates insulin secretion through central muscarine signaling, which leads to increased food intake; it also inhibits fat breakdown to cause fat accumulation in the body, resulting in obesity." (PMID 39830328, 2024). "Moreover, in patients with PCOS, obesity is associated with an increase in pro-inflammatory cytokines, insulin resistance, and apoptosis of ovarian granulosa cells." (PMID 38848344, 2024). "Insulin and leptin are associated with the development of obesity." (PMID 39906039, 2024). "Specifically, evaluating how this therapy affects the expression of genes and proteins associated with obesity, insulin sensitivity, and fat metabolism could yield critical data that advances our ability to tailor treatments to individual patients." (PMID 39544552, 2024). "Another study showed that Nr2e1 could function as a target for improving insulin sensitivity and inflammation in obesity and associated problems." (PMID 39408930, 2024).
Obesity (continued). "Selective leptin resistance, decreased levels of ghrelin (a hormone associated with hunger), and elevated levels of insulin collectively may play a role in driving the sympathetic activation observed in individuals with obesity." (PMID 39411599, 2024). "Similarly, a 12-week diet-induced weight loss program has been shown to reverse the downregulation of the obesity-associated lncRNA p19461, suggesting its potential as a biomarker for successful weight loss and improved insulin sensitivity." (PMID 39765643, 2024). "Therefore, the assessment of the effect of the presence of IL6 and INS polymorphisms in patients with obesity or T2D seems to be an interesting and justified endeavour." (PMID 38250713, 2024). "For example, increased levels of unbound IGF-1 protein are caused by obesity-related insulin resistance and hyperinsulinemia, which may also trigger the insulin and IGF-1 receptor signal transduction pathways, which may ultimately lead to tumor growth." (PMID 38835644, 2024). "Obesity, characterized by increased adiposity, has been associated with the induction of inflammation in adipose tissues, leading to metabolic syndromes and the impairment of insulin sensitivity in major tissues." (PMID 38790945, 2024). "PTEN mutations are associated with obesity and with a paradoxically enhanced insulin sensitivity." (PMID 39120327, 2024). "Additionally, skeletal muscle mechanisms such as mitochondrial dysfunction, oxidative stress, and energy metabolism, along with other factors, are intricately linked to T2DM and its pathological manifestations like obesity, IR, and insulin sensitivity." (PMID 39634184, 2024). "Interestingly, insulin signaling is a major factor linking obesity to cancer progression and has been implicated in resistance to chemotherapy." (PMID 39622796, 2024). "Thus, the implementation of new therapeutic approaches to prevent or counteract the obesity-associated inflammation and disrupted insulin signaling is encouraged, especially given that the world’s population is aging rapidly." (PMID 38794136, 2024). "Senolytic therapy with dasatanib + quercetin (D + Q) in HFD-induced murine obesity is associated with improvement in cellular senescence markers, insulin sensitivity, metabolic syndrome, metaflammation, WAT macrophage infiltration, and adipogenesis in preclinical studies." (PMID 39063184, 2024). "However, mixed findings surround the idea that inflammation caused by obesity disrupts insulin signaling in BMAT." (PMID 39188529, 2024). "Similarly, a study has found comparable neuropathy risks in individuals with long-standing Type 1 diabetes linked to obesity, where elevated BMI and poor lipid profiles contribute to nerve dysfunction via insulin resistance and systemic inflammation." (PMID 39559714, 2024). "Specifically, ceramides (Cer 16:0 and Cer 18:0) have been described as increased in people with obesity and may be negatively associated with insulin sensitivity and body energy expenditure." (PMID 39195494, 2024). "Additionally, cancer treatments can lead to alterations in insulin sensitivity, endothelial damage, lipid metabolism, hormone deficiencies, and obesity, all metabolic dysfunctions that contribute to developing metabolic syndrome." (PMID 39335119, 2024). "When factors such as obesity, inflammatory reactions, and lipid accumulation cause overloading and disruption in insulin signaling, IR may occur." (PMID 39201722, 2024). "First, metabolic challenges in the form of congenital or diet-induced obesity in mice revealed hepatic zinc deficiency along with associated comorbidities including hepatic steatosis, increased fasting blood glucose, and impaired insulin sensitivity." (PMID 39671241, 2024). "Obesity is associated with impaired glucose metabolism and hepatic insulin resistance." (PMID 38989003, 2024).
Obesity (continued). "In addition, we identified 40 proteins significantly differentially expressed with obesity, most of which were also shown strong associations with insulin-related traits and lipid profiles." (PMID 38548792, 2024). "Although obesity is simplistically described as an excessive accumulation of fat in the body, its pathophysiology is more complex, with underlying low-grade chronic inflammation, oxidative stress and insulin resistance as important components." (PMID 39330507, 2024). "Even though raised CVD risk may be partially linked to fructose-related obesity or insulin-resistant conditions, direct fructose toxicity to the cardiovascular system is also possible." (PMID 38305829, 2024). "There is much evidence which suggests that changes in the composition of gut microbiota may affect the host’s energy homeostasis, systemic inflammation, lipid metabolism, and insulin sensitivity in obesity and obesity-associated disorders, such as T2DM." (PMID 39683552, 2024). "In obesity, chronic inflammation of the islets, and glucotoxicity resulting from high basal insulin levels, would cause progressive β-cell dysfunction, inducing apoptosis and cellular dedifferentiation, identified as the central trigger for the development of T2D." (PMID 38942960, 2024). "Furthermore, the endogenous upregulation of GDF-15 is associated with resistance to diet-induced obesity, improved glucose homeostasis, and increased insulin sensitivity." (PMID 38791028, 2024). "In this vein, a series of tests regarding functional, safety, and technological criteria were applied, in order to overall assess the effectiveness of novel strains isolated from various sources, targeting mainly their ability to manage obesity-associated insulin resistance." (PMID 38399636, 2024). "To date, the FTO gene has been proposed as a candidate gene to affect fat oxidation during exercise because of the association of the “at-risk” A allele with different obesity-related factors such as increased body fat, higher appetite and elevated insulin and triglyceride levels." (PMID 39858551, 2024). "BMI enrichment in EndoC-BH1 cells is consistent with the insulin–obesity association." (PMID 39240351, 2024). "However, the metabolic responses of horses and humans to insulin dysfunction are potentially similar, especially when factors such as obesity, age, and sex are implicated." (PMID 38886475, 2024). "Notably, the loss of TNF-alpha has been linked to improved insulin sensitivity and protection against obesity-related reduction in insulin receptor signaling in obese mice." (PMID 39120321, 2024). "Simultaneously, obesity is linked to dyslipidemia, while the administration of insulin therapy may induce weight gain, thereby negatively impacting the regulation of blood lipids in patients." (PMID 39398332, 2024). "Adiponectin is primarily released by the visceral adipose tissue and is the most abundant adipokine, with quantities in the bloodstream inversely associated with obesity, which specifically exerts anti-apoptotic, anti-inflammatory/anti-fibrotic, and insulin-sensitizing effects." (PMID 37056282, 2023). "Furthermore, we found that ApoE deficiency mice globally prevented obesity by restraining adipose tissue expansion and improved systemic glucose tolerance and insulin sensitivity." (PMID 38062308, 2023). "How does obesity cause systemic insulin insensitivity and hyperglycemia?" (PMID 36920797, 2023). "Thus, for East Asians, it is essential to suppress excessive insulin secretion to maintain β cell function and potentially lower the risk of obesity, T2DM, cancer, and Alzheimer’s disease." (PMID 36904173, 2023). "Metabolic dysfunction may explain the association between MAFLD and CKD30,31, and obesity is known to have the potential to cause CKD due to the secretion of adipokines that increase hepatic insulin resistance and chronic inflammation." (PMID 36720976, 2023).
Obesity (continued). "Obesity development has been associated with high insulin levels, leading to hyperinsulinemia." (PMID 37512149, 2023). "Notably, obesity is associated with hyperinsulinemia and perhaps, elevated insulin levels are involved in upregulation of adipose Mettl14 and m6A modifications in obesity." (PMID 37526326, 2023). "Some research suggests that obesity-associated chronic inflammation comes from altered physiology of adipose tissue (AT), resulting in low-systemic insulin resistance and metabolic dysfunction that, in consequence, may lead to brain dysfunction." (PMID 37432552, 2023). "This apparent disparity between blood glucose and insulin levels led to the hypothesis that hyperinsulinemia is the initial, primary effect of overeating and obesity and is caused by stimulation of insulin secretion and suppression of its degradation." (PMID 36902173, 2023). "Furthermore, obesity, which is associated with reduced insulin sensitivity, can lead to peripheral hyperglycemia, contributing to cognitive dysfunction and neuron death in animal models." (PMID 37623897, 2023). "How obesity causes insulin insensitivity and hyperglycemia is a long-standing question." (PMID 36920797, 2023). "However,single agonist peptides activating GLP-1R to stimulate insulin secretionalso suppress obesity-linked glucagon release." (PMID 37523325, 2023). "As mentioned in Section 2, obesity induced by a 23-week high-fat and high-sucrose diet was mitigated in liver-specific Usp20KO mice, indicating that liver-specific Usp20 deficiency caused significant restoration of glucose and insulin tolerance." (PMID 36834633, 2023). "Thus, an increase in the expression and functional activity of phosphatases PTP1B and TC-PTP and JNK1 kinase, which reduces the efficiency of insulin signaling, is one of the causes of peripheral and central IR, including in obesity, MS, and T2DM." (PMID 36834685, 2023). "Moreover, insulin and IGF-1 stimulate protein synthesis in the skeletal muscles of mice, and impaired insulin activity in skeletal muscles is linked to obesity and sarcopenia." (PMID 37237929, 2023). "Furthermore, among the many identified miRNAs involved in metabolism and metabolic diseases, miR-122-5p, miR-34a-5p, and miR-125b-5p possess specific expression patterns and functions associated with obesity, insulin resistance and inflammatory states." (PMID 36875756, 2023). "However, a previous meta-analysis identified associations between metformin and accelerated growth postnatally, leading to an increased risk of obesity in childhood, compared with children of women treated with insulin during pregnancy." (PMID 37442824, 2023). "Recent studies have shown that autophagy is an important regulator of organelle function and insulin signaling, and that loss of autophagy is a key component of defective insulin action in obesity, which may be specifically related to ER function." (PMID 37056675, 2023). "Furthermore, IL-33 administration reduces adiposity, while also attenuating insulin and glucose intolerance caused by obesity." (PMID 36994095, 2023). "The mechanisms of obesity-associated chronic inflammation are complex, and currently tissue hypoxia, oxidative stress, endoplasmic reticulum stress, insulin resistance, and gut microbial changes are among the pathways that can explain obesity-associated chronic inflammation." (PMID 37403139, 2023). "That is, sTfR levels may be affected by mechanisms other than those related to Fe metabolism (such as insulin sensitivity and obesity), and they could be causally linked to T2DM." (PMID 37111154, 2023). "Similarly, genetic variations in the GCKR expression can also regulate glucose metabolism and insulin sensitivity in obesity-associated metabolic disorders including NAFLD and T2DM." (PMID 37829557, 2023). "Several previous studies found that eating fast could increase the risk of obesity and metabolic syndrome due to a reduction in insulin sensitivity." (PMID 36875835, 2023).
Obesity (continued). "These putative effector genes of obesity-associated methylation changes cluster in developmental, metabolic and inflammatory pathways, and encode proteins with key roles in adipogenesis, browning/beigeing of white adipocytes and insulin signalling." (PMID 37188674, 2023). "However, our observation is consistent with previous studies in adults and children with obesity showing that baseline levels of a BCAA‐related PCA‐factor predicts improvements in insulin sensitivity in response to behavioural weight loss interventions." (PMID 36415168, 2023). "Considering another novel adipokine first described in 2016, asprosin is noted for inducing the synthesis of hepatic glucose, promoting islet β-cell inflammation, and inhibiting the secretion of insulin while raising glucose, and is regarded to be closely linked to obesity." (PMID 38069063, 2023). "Although the association between elevated insulin levels and obesity initiated the concept of the current study protocol, the trial did not aim to test a hypothetic metabolic mechanism or to determine the glycaemic index (GI) or the glycaemic last (GL) of the study breads." (PMID 36904300, 2023). "INS is a well-known factor related to high-risk BC patients who have obesity." (PMID 37895140, 2023). "The insulin-dependent enzyme lipoprotein lipase, which limits the clearance of triglycerides and the leakage of FFAs from the adipocyte, has reduced activity in people with obesity, causing the hampered insulin-dependent esterification of FFAs in the adipose tissue." (PMID 36980074, 2023). "Additionally, it's associated with many DM-related risk factors, including decreased insulin sensitivity, obesity, high blood pressure, subclinical inflammation and metabolic syndrome, all of which can increase the risk of developing DM." (PMID 37543637, 2023). "According to the role of obesity in metabolic syndrome, the high risk of moderate/severe ED may be due to pathophysiologic processes, including oxidative stress, inflammation, and insulin and leptin resistance." (PMID 37065736, 2023). "Although insulin sensitivity and liver enzymes were associated with FT, women with obesity showed lower M (coef = 8.56 − 0.080(FT) − 3.71(Ob); p < 0.001) and higher aspartate aminotransferase (coef = 26.27 + 0.532 (FT) + 8.08 (Ob); p = 0.015) than lean women with the same level of FT." (PMID 37763087, 2023). "Obesity increased significantly in dogs between 2011 and 2020, being an important predisposing factor for insulin-resistant DM, as it interferes with glucose and insulin homeostasis." (PMID 36830471, 2023). "Interestingly, as IR is primarily associated with obesity, prediabetes, and T2D, people with type 1 diabetes (T1D) can also become insulin resistant." (PMID 37372966, 2023). "However, protein tyrosine phosphatase-1B (PTP1B), an intracellular protein that inhibits insulin and leptin signaling, has been shown to promote inflammation caused by obesity." (PMID 37153549, 2023). "It is unclear whether relative insulin shortage or pronounced insulin resistance is linked to poor cardiometabolic problems like obesity." (PMID 37274075, 2023). "In addition, physiological changes such as inflammation and reduced insulin and dopamine levels caused by obesity are also major potential mechanisms for obesity-induced cognitive decline." (PMID 37663339, 2023). "The strongest predictors among the biochemical parameters of obesity risk were insulin and leptin." (PMID 37373485, 2023). "Obesity in pregnancy associates with changes in the glucose-insulin axis." (PMID 37029207, 2023). "Obesity causes a decrease in growth hormone (GH) levels and an increase in insulin levels." (PMID 37189668, 2023). "Regular PA is associated with improved insulin sensitivity and may be encouraged not only in adolescents with obesity or metabolic disorders but also to prevent adverse metabolic outcomes in normal-weight adolescents." (PMID 37396186, 2023).